IL6 (interleukin 6)
Diseases named in the same sentence as IL6 in open-access papers (continued):
Sharing a sentence is not in itself a finding about the gene and the disease.
liver disease (continued). "Therefore, a longitudinal study could aid in more precise detection of the actual impact of IL-6 levels and TLR2 rs3804099 SNP variation on liver disease progression and outcome in HBV patients." (PMID 39071840, 2024). "In general, IL-6 binds to the interleukin-6 receptor (IL-6R), and the IL-6/IL-6R complex initiates glycoprotein 130 (gp130) for the activation of JAK/STAT, MAPK and PI3K/AKT, which is essential for the early onset of liver disease and the progression and maintenance of the regenerative process." (PMID 35955794, 2022). "In addition, proinflammatory cytokines (IL-1, IL-6, IL-23, TNF) and the imbalance in T-cell subtypes, such as T helper 17/T regulatory cell, promote hepatic inflammation and induction of fibrosis, leading to the potential development and progression of liver disease." (PMID 41209843, 2026). "However, its diagnostic value is limited as albumin levels may be influenced by various factors, including liver disease, gastrointestinal and renal losses, and inflammatory states characterized by high levels of tumor necrosis factor-alpha (TNF-α) and interleukin 6 (IL-6)." (PMID 38021540, 2023). "However, the role of ILC2-derived IL-6 for liver disease pathology is not clear." (PMID 31974518, 2020). "Therefore, portal hypertension does not affect IL-6 levels in patients with ascites." (PMID 28661458, 2017). "PBC patients have been reported to have higher serum levels of gut endotoxins/lipopolysaccharide, with increased expression of toll-like receptor (TLR) 4 and pro-inflammatory cytokines TNF-α, IL-1β, IL-6, and IL-8 compared to non-PBC liver disease." (PMID 39859319, 2025). "When comparing patients with clinically significant portal hypertension (CSPH, HVPG ≥ 10 mmHg) to patients without CSPH, there were significantly enhanced serum levels of IL-6 and IL-18 in the former group." (PMID 38077228, 2023). "This confirmed a mechanism: IL-6 major through p-STAT3 rather than p-STAT1 pathway affecting severity of inflammation and carcinogenesis in liver disease, particularly in HCC patients." (PMID 25908103, 2015). "IL-6 levels, along with those of IL-8 and IL-10, are increased in patients with ALD who have no clinical signs of liver disease." (PMID 26695748, 2015).
multiple sclerosis (202 papers, 2008 to 2026). A progressive autoimmune disorder affecting the central nervous system resulting in demyelination. "For instance, IL-6 is increased in multiple sclerosis (MS) patients with an acute relapse, and it is implicated in T cell dysfunction." (PMID 40717732, 2025). "Thirdly, genetic susceptibility to multiple sclerosis (MS) was linked to higher IL-6 responses through the QRSL1 locus." (PMID 38714679, 2024). "A cluster of inflammation markers composed of blood leukocytes, CRP, and blood cell gene expression of IL17A and IL6 was positively associated with a cluster of multiple sclerosis-related species." (PMID 36604748, 2023). "The pathway k556 most correlated with Lactobacillus ruminis was reported to be implicated in multiple sclerosis, which is closely related to diet and IL-6." (PMID 35422001, 2022). "Particularly, in patients with advanced cancer or multiple sclerosis, IL-6 was the most significant cytokines associated with fatigue." (PMID 36193420, 2022). "Stat3 is induced by IL6 canonical signaling in CD4+ T cells and IL6/Stat3 axis signaling contributes to the development of Th17 cells and is associated with several human diseases, such as multiple sclerosis (MS) and RA." (PMID 35126382, 2021). "The dysregulation of tight junctions leads to altered barrier function resulting in changes in levels of inflammatory cytokines such as IFN-α, IFN-γ, IL-6, and IL-1β as seen in inflammation-associated diseases such as multiple sclerosis and cancer." (PMID 35046947, 2021). "On the other hand, IL-6-deficient mice are resistant to experimental autoimmune encephalomyelitis, an animal model of multiple sclerosis, highlighting the pro-inflammatory functions of IL-6 in CNS autoimmune disease." (PMID 28438224, 2017). "Multiple sclerosis development, however, has been reported in a patient under anti-IL6 treatment, leading to suspect a causal association." (PMID 27266518, 2016). "The IL-6 gene polymorphism (-174 G/C, rs1800795), which is functional with the G allele increasing IL-6 production, has been found to be associated amongst others with toxoplasmic retinochoroiditis and multiple sclerosis." (PMID 26640809, 2015). "In previous studies, TNFα, IL-1β, and IL-6 have been implicated as mediators of multiple sclerosis pathology." (PMID 23861993, 2013). "Additionally, IL-6 is known to amplify inflammation and neuroinflammation in diseases such as multiple sclerosis and HIV-associated neurocognitive disorders." (PMID 41150766, 2025). "IL-6 has been implicated in the pathogenesis of neurodegenerative disorders with profound neuropathological changes; including Alzheimer’s, Parkinson’s, and multiple sclerosis; where elevated IL-6 expression have been observed." (PMID 37779624, 2023). "We explored whether genetically predicted increased body mass index (BMI) modulates multiple sclerosis (MS) risk through interleukin-6 (IL-6) signaling." (PMID 35386698, 2022). "Our results indicate that the IL6 pathway alteration is involved in neurological deficit increase and Tregs imbalance in resting and activated conditions in untreated male and female patient groups, underlining the autoimmune etiology of multiple sclerosis." (PMID 23148845, 2012). "Similarly, hematopoietic EP4-deficiency reduces inflammation in a mouse model of multiple sclerosis through a mechanism likely involving reduced IL-6 production, and EP4 is required for initiation of skin immune responses after antigen exposure by promoting migration of skin dendritic cells." (PMID 27351842, 2016). "Indeed, our data indicate that IL6 pathways are also involved in T regulatory (Treg) cell imbalance and an increase in neurological deficit in both men and women groups of MS patients, underlining the autoimmune etiology of multiple sclerosis." (PMID 23148845, 2012). "In ex vivo cultures, curcumin significantly inhibited IL-6 production in macrophages derived from patients with multiple sclerosis (MS) and healthy donors." (PMID 42198213, 2026).
multiple sclerosis (continued). "Elevated IL-6 levels in the CSF were found in individuals with progressive MS, and CSF IL-6 showed positive correlations with the Expanded Disability Status Scale, the Multiple Sclerosis Severity Score, and CSF glial fibrillary acidic protein levels." (PMID 40175894, 2025). "IL-6 showed positive correlations with the Expanded Disability Status Scale and the Multiple Sclerosis Severity Score." (PMID 40427596, 2025). "For example, T cells can cross the BBB and attack myelin via MMP-9, together with B-cell-derived IL-6, leading to astrocyte reactivity and thus resulting in demyelination in multiple sclerosis." (PMID 41425563, 2025). "OSM is a member of the IL-6 cytokine family and has previously been shown to play a neuroprotective role in spinal cord injury and multiple sclerosis (MS)." (PMID 41562085, 2025). "In support, carvacrol treatment was shown to down-regulate IFN-γ expression in splenocytes of asthmatic mice and to decrease IFN-γ and IL-6 secretion in mice suffering from multiple sclerosis." (PMID 38343716, 2024). "Classical monocytes have been reported to display a more proinflammatory phenotype producing the highest levels of various cytokines including IL-6 and being significantly more abundant in patients with multiple sclerosis (MS), PD and ALS." (PMID 38305941, 2024). "A previous study on multiple sclerosis also reported that CSF IL‐6 and CSF leptin levels were higher in obese patients." (PMID 39401137, 2024). "Analysis in this study showed that interleukin-6 (IL-6) levels in the cerebrospinal fluid of patients diagnosed with de novo multiple sclerosis (MS) were significantly higher compared to the healthy population." (PMID 39000506, 2024). "Increased levels of TNFα, IL-6 and IL-10 were evident in the blood of an LPS-treated animal model of multiple sclerosis." (PMID 37999377, 2023). "CSF levels of TNF-α, CXCL9, and IL-6 are also elevated in other neuroinflammatory diseases such as multiple sclerosis." (PMID 37304071, 2023). "hAAT was previously shown to reduce axon demyelination and secreted IL-6 levels in a mouse model of EAE-induced multiple sclerosis, which is consistent with the effects observed in our CMT1A mouse model." (PMID 35806409, 2022). "Overproduction of IL-6 has been described in several inflammatory and immune disorders such as multiple sclerosis." (PMID 32023844, 2020). "MiR-455-5p is negatively correlated with the activation of the NF-κB pathway, thus inhibiting the expression of IL-1β, IL-6 and IL-8 and in turn ameliorating the severity of multiple sclerosis." (PMID 31304055, 2019). "The increased IL-6 observed in the supplemented children is consistent with IL-6 up-regulation in the peripheral blood mononuclear cells of vitamin D supplemented multiple sclerosis patients." (PMID 31709259, 2019). "Second, we assess the astrocytic response to IL-1β, TNF-α, and IL-6, all cytokines important in neuroinflammation, such as multiple sclerosis." (PMID 30409508, 2018). "For example, cannabinoid receptor agonists can inhibit neuronal demyelination in a mouse model of multiple sclerosis by promoting interleukin-6 accumulation which is known to be neuroprotective." (PMID 28545594, 2017). "It has been reported that B cells can produce the inflammatory cytokine IL-6 and contribute to the pathogenesis of multiple sclerosis." (PMID 28824639, 2017). "GM-CSF, IL6, and TNFα are well known as proinflammatory cytokines and are upregulated in various kinds of white matter diseases, including multiple sclerosis (MS) and neuromyelitis optica (NMO)." (PMID 27402089, 2016). "In this study, we executed an experimental autoimmune encephalomyelitis (EAE) model known as a murine model of multiple sclerosis, because IL-6 has been shown to be responsible for EAE development." (PMID 27211851, 2016).
multiple sclerosis (continued). "In order to test the role of astrocytic IL-6 in neuroinflammation, we studied an extensively-used animal model of multiple sclerosis, experimental autoimmune encephalomyelitis (EAE), in mice with an IL-6 deficiency in astrocytes (Ast-IL-6 KO)." (PMID 27196935, 2016). "Regarding anti-IL-6 treatment the FDA lists nervous system problems including multiple sclerosis as possible serious side effects of tocilizumab." (PMID 26640809, 2015). "Recent provocative data in a multiple sclerosis murine model suggests that IL6 producing B cells contribute to T cell stimulation in the disease, including Th17 polarization, and BCDT ameliorated the disease only in mice with IL6-sufficient B cells." (PMID 26047509, 2015). "In contrast infiltration of T cells occurs in multiple sclerosis and PD, and levels of IL-1β, IL-6 and TNF-α are elevated in the cerebrospinal fluid of PD patients." (PMID 26634899, 2015). "Evidence suggests that low BDNF is correlated with high IL-6 in the cognitive dysfunction of multiple sclerosis patients." (PMID 25525451, 2014). "Previous studies have shown that cytokines, including IL2 and the TH17 skewing cytokines (IL23, IL6, TGFβ), are abnormally present in the CSF of some patients with multiple sclerosis as well as in mice immunized for EAE." (PMID 25153088, 2014). "In a similar way as in RA, IL-6 also influences the development and onset of experimental autoimmune encephalomyelitis, the murine model for multiple sclerosis (MS)." (PMID 24155968, 2013). "The roles of cytokines, such as IFN-γ, TNF-α, IL-1β and IL-6, expressed in inflammatory diseases such as multiple sclerosis are complex." (PMID 18793322, 2008). "Futher, corticosteroid-based treatments show effective anti-inflammatory efficacy as therapeutic agents for infectious diseases of the brains and in mouse model of multiple sclerosis, significantly down-regulating pro-inflammatory cytokines such as IL-1β, IL-6, IL-17, IFN-γ, and TNF-α." (PMID 40390112, 2025). "However, in experimental models of multiple sclerosis, fenofibrate reduced expression of IL-2, IL-6 and key Toll-like receptor signaling components (including CD14), thereby decreasing microglial activation and pro-inflammatory mediator secretion." (PMID 41009625, 2025). "Elevations in CSF IL‐6 are widely observed in neuroinflammation and are reported to correlate with the prognosis of neurological diseases such as traumatic brain injuries, multiple sclerosis, and neuro‐Behçet's syndrome." (PMID 39317977, 2024). "The study additionally found a positive correlation between IL-6 levels in the cerebrospinal fluid and the number of MRI lesions of the thoracic spine enhancing after contrast administration in patients diagnosed with de novo multiple sclerosis." (PMID 39000506, 2024). "Elevated IL-6 was also detected in children with multiple sclerosis who received VD3." (PMID 36904187, 2023). "Multiple sclerosis (MS)-associated retroviral element (MSRV) is an endogenous retrovirus belonging to the HERV-W family, and its expression correlates with that of the inflammatory cytokines, interleukin-6 (IL-6) and IL12p40, in patients with MS." (PMID 38136578, 2023). "Elevated levels of IL-1β and IL-6 have also been observed in patients with multiple sclerosis." (PMID 36675141, 2023). "Particularly, in neurobrucelosis, infiltrating CD8+ T-cells could also be a source of IL-6, as it has been described in multiple sclerosis." (PMID 38322014, 2023). "In multiple sclerosis, PE decreased IL-6 and increased TGF-β expression in patients." (PMID 35514988, 2022). "The IL-2:IL-6 ratio, IL-2, and chitinase 3-like 2 (all in cerebrospinal fluid) might be of value as prognostic biomarkers in early phases of multiple sclerosis." (PMID 35759479, 2022). "Likewise, fumarates had differing effects on the expression of key genes that have been linked to multiple sclerosis (e.g., TNFAIP3, CXCL8, IL6, and IRF1)." (PMID 35455458, 2022).
multiple sclerosis (continued). "Bone marrow mesenchymal stem cells can improve the symptoms of patients with multiple sclerosis by inhibiting the inflammatory response in the central nervous system, regulating the expression of interleukin 6, stimulating the production of nerve growth factor, and protecting axons." (PMID 35371265, 2022). "WIN-mediated attenuation of IL-6 expression leading to a decrease in neuroinflammation was also described in aged rats and in an experimental autoimmune encephalomyelitis model mimicking essential pathological features with multiple sclerosis." (PMID 32074976, 2020). "While the cytokine profile of CSF from VZV myelopathy patients has not been extensively characterized, in another central nervous system disease produced by VZV (VZV vasculopathy), CSF contains increased levels of IL-6 and IL-8 compared to CSF from normal patients and those with multiple sclerosis." (PMID 30442152, 2018). "Furthermore, a clinical study demonstrated that fish oil decreased serum levels of TNF-alpha, IL-1beta, IL-6, and nitric oxide metabolites in multiple sclerosis patients treated with IFN-1beta." (PMID 27313881, 2016). "Notably, B cells from multiple sclerosis (MS) patients also produced more IL6, an abnormality that was normalized with B cell reconstitution after rituximab." (PMID 26047509, 2015). "This transient increase in choroidal IL-6 mRNA is similar to that observed for plasma IL-6 following strenuous exercise, following ischemic brain injuries, surgical trauma, and in a subset of patients with multiple sclerosis following treatment with interferon-β." (PMID 34608867, 2021). "This is in line with previous reports showing that C/EBPδ is involved in the regulation of IL-6 and IL-10 after LPS stimulation, although C/EBPδ suppresses IL-10 expression in dendritic cells of the central nervous system in an animal model of multiple sclerosis." (PMID 25958220, 2015). "In a multiple sclerosis mouse model, ER stress-induced activation of the JAK1–STAT3 axis led to the expression of interleukin 6 and several chemokines, and the activation of STAT3 signaling was dependent on PERK." (PMID 40384344, 2025). "On the other hand, pro-inflammatory cytokines such as IL-6, IL-1β, IL-17, IL-22, TNF-α, IL-12, and IFN-γ are thought to play a pivotal role in the pathogenesis of multiple sclerosis (MS) through various signaling pathways." (PMID 40507498, 2025). "A placebo-controlled study involving human patients with multiple sclerosis demonstrated that coenzyme Q10 supplementation significantly decreased TNF-α and IL-6 levels compared to the placebo group." (PMID 40520426, 2025). "In Multiple Sclerosis (MS), CBD in preclinical models of MS resulted in a reduction of proinflammatory cytokines such as IL-17A, IFN-γ, TNF-α, IL-6 and IL-1b and an increase in anti-inflammatory cytokines such as IL-4, IL-10 and TGF-β." (PMID 38601151, 2024). "Meanwhile, inflammatory factors expressed in the brain, such as IL-6 and IFN-γ in the cerebral white matter, can activate inflammatory responses, leading to neurodegeneration and the onset of multiple sclerosis." (PMID 35755996, 2022). "Vitamin D3 supplementation was found to improve multiple sclerosis by downregulation of both IL17A and IL6 levels." (PMID 36233290, 2022). "In T lymphocytes, IL-6 directly inhibits gp190 transcription, biasing lineage maturation toward TH17 immunity, TH17 being an initiating driver of multiple sclerosis in human and EAE in animal models." (PMID 35047909, 2021). "We show the effect of selective recovery of IL-6 expression in microglia by crossing IL6-DIO-KO with Cx3cr1-CreER mice in the context of experimental autoimmune encephalomyelitis (EAE), the most popular mouse model of multiple sclerosis (MS)." (PMID 33059703, 2020). "At least, inflammatory cytokines such as IL-6 were elevated in CSF from ALS patients compared with control donors and patients with multiple sclerosis." (PMID 30630471, 2019).